ATP6V1B1 (ATPase H+ transporting V1 subunit B1)
Description:
Non-catalytic subunit of the V1 complex of vacuolar(H+)- ATPase (V-ATPase), a multisubunit enzyme composed of a peripheral complex (V1) that hydrolyzes ATP and a membrane integral complex (V0) that translocates protons. V-ATPase is responsible for acidifying and maintaining the pH of intracellular compartments and in some cell types, is targeted to the plasma membrane, where it is responsible for acidifying the extracellular environment. Essential for the proper assembly and activity of V-ATPase. In renal intercalated cells, mediates secretion of protons (H+) into the urine thereby ensuring correct urinary acidification. Required for optimal olfactory function by mediating the acidification of the nasal olfactory epithelium (By similarity).
Synonyms: ATP6B1; VATB; VPP3; RTA1B; Vma2; DRTA2
Tractability: Small molecule: it belongs to a druggable protein family. Antibody: UniProt places it where antibodies can reach, with high confidence; its Gene Ontology location is reachable by antibodies, with medium confidence. PROTAC: ubiquitination databases record sites on it; a small molecule that binds it is known.
Target class: Enzyme; Hydrolase
Gene: Protein-coding gene on chromosome 2 (70,935,771 to 70,965,431, forward strand). Ensembl gene ENSG00000116039.
Subcellular location: Apical cell membrane; Basolateral cell membrane
Subcellular location (Human Protein Atlas): Nuclear membrane; Nucleoplasm
Pathways (Reactome):
Transport of small molecules: Ion channel transport; Transferrin endocytosis and recycling
Cellular responses to stimuli: Amino acids regulate mTORC1
Immune System: ROS and RNS production in phagocytes
Signal Transduction: Insulin receptor recycling
Gene Ontology:
Molecular function: protein binding; proton transmembrane transporter activity; ATP binding; protein-containing complex binding; proton-transporting ATPase activity, rotational mechanism
Biological process: calcium ion homeostasis; inner ear morphogenesis; ossification; pH reduction; proton transmembrane transport; regulation of pH; renal tubular secretion; sensory perception of sound; vacuolar proton-transporting V-type ATPase complex assembly; regulation of macroautophagy; vacuolar acidification; ATP metabolic process; synaptic vesicle lumen acidification
Cellular component: apical plasma membrane; extracellular exosome; vacuolar proton-transporting V-type ATPase complex; vacuolar proton-transporting V-type ATPase, V1 domain; basolateral plasma membrane; cytoplasm; cytosol; lateral plasma membrane; microvillus; plasma membrane; extrinsic component of synaptic vesicle membrane; membrane; proton-transporting V-type ATPase, V1 domain
Genetic constraint (gnomAD): Loss-of-function variants: 41 observed, 64.29 expected, observed/expected ratio (o/e) 0.64, 90% interval 0.5 to 0.83. The upper end of that interval is the gene's LOEUF score, 0.83, which puts it in group 3 of 6, group 1 being the genes least tolerant of losing a copy. Missense variants: 651 observed, 726.4 expected, observed/expected ratio (o/e) 0.9, 90% interval 0.84 to 0.96. Synonymous variants: 253 observed, 285.95 expected, observed/expected ratio (o/e) 0.88, 90% interval 0.8 to 0.98.
Gene-disease validity (ClinGen):
ClinGen rates the evidence that ATP6V1B1 causes each of these diseases.
renal tubular acidosis, distal, 2, with progressive sensorineural hearing loss (autosomal recessive): Definitive.
Homologues: Orthologues: chimpanzee ATP6V1B1 (99% identical), macaque ATP6V1B1 (99% identical), guinea pig ATP6V1B1 (95% identical), rabbit ATP6V1B1 (95% identical), rat Atp6v1b1 (94% identical), mouse Atp6v1b1 (94% identical), dog ATP6V1B1 (87% identical), tropical clawed frog atp6v1b1 (87% identical), pig ATP6V1B1 (85% identical), Caenorhabditis elegans vha-12 (78% identical), Caenorhabditis elegans spe-5 (72% identical). Paralogues in human: ATP6V1B2 (85% identical), ATP5F1B (25% identical), ATP6V1A (25% identical), ATP5F1A (24% identical).